IGLV5-37 (immunoglobulin lambda variable 5-37)
Description:
V region of the variable domain of immunoglobulin light chains that participates in the antigen recognition. Immunoglobulins, also known as antibodies, are membrane-bound or secreted glycoproteins produced by B lymphocytes. In the recognition phase of humoral immunity, the membrane-bound immunoglobulins serve as receptors which, upon binding of a specific antigen, trigger the clonal expansion and differentiation of B lymphocytes into immunoglobulins-secreting plasma cells. Secreted immunoglobulins mediate the effector phase of humoral immunity, which results in the elimination of bound antigens. The antigen binding site is formed by the variable domain of one heavy chain, together with that of its associated light chain. Thus, each immunoglobulin has two antigen binding sites with remarkable affinity for a particular antigen. The variable domains are assembled by a process called V-(D)-J rearrangement and can then be subjected to somatic hypermutations which, after exposure to antigen and selection, allow affinity maturation for a particular antigen.
Synonyms: IGLV537; V4-1
Gene: Immunoglobulin variable (V) gene on chromosome 22 (22,427,540 to 22,428,035, forward strand). Ensembl gene ENSG00000211654.
Subcellular location: Secreted; Cell membrane
Gene Ontology:
Biological process: immune response
Cellular component: extracellular region; immunoglobulin complex; plasma membrane
Homologues: Paralogues in human: IGLV5-45 (86% identical), IGLV5-52 (76% identical), IGLV5-48 (74% identical), IGLV11-55 (72% identical), IGLV4-60 (59% identical), IGLV4-69 (58% identical), IGLV2-18 (55% identical), IGLV2-8 (54% identical), IGLV3-21 (54% identical), IGLV1-40 (54% identical), IGLV2-11 (54% identical), VPREB1 (54% identical), and 81 more.